ENSG00000285330 (novel protein)
Gene: Protein-coding gene on chromosome 4 (109,713,916 to 109,801,999, reverse strand). Ensembl gene ENSG00000285330.
Genetic constraint (gnomAD): Loss-of-function variants: 51 observed, 57.41 expected, observed/expected ratio (o/e) 0.89, 90% interval 0.71 to 1.12. Missense variants: 548 observed, 569.1 expected, observed/expected ratio (o/e) 0.96, 90% interval 0.9 to 1.03. Synonymous variants: 196 observed, 191.57 expected, observed/expected ratio (o/e) 1.02, 90% interval 0.91 to 1.15.